TNF (tumor necrosis factor)
Diseases named in the same sentence as TNF in open-access papers (continued):
Sharing a sentence is not in itself a finding about the gene and the disease.
Hepatic steatosis (continued). "Contrary to RANKL and LIGHT, which appear to promote MASLD, tumor necrosis factor weak inducer of apoptosis (TWEAK) was shown to downregulate TNF-α-induced inflammatory signals and ameliorate IR and hepatic steatosis, thus implying a potentially beneficial effect in MASLD." (PMID 40794228, 2025). "We measured changes in hepatic steatosis, non-invasive fibrosis scores, inflammatory markers (including interleukin-6, tumor necrosis factor-alpha, and highly sensitive C-reactive protein), liver enzymes, and lipid profiles at baseline and at the end of the 24 weeks." (PMID 41011150, 2025). "In alcohol-associated hepatic steatosis, ROS-induced oxidative stress may suppress energy metabolism signaling pathways linked to AMPK and Sirt1, while promoting the production of TNF-α." (PMID 39334796, 2024). "They found that chronic alcohol-fed TLR4 knockout mice showed reduced liver damage, including less hepatic steatosis, lower levels of liver enzymes, and decreased expression of liver TNF-α, IL-6, IRF3, and IRF7 compared to WT, TLR2 knockout, and MyD88 knockout mice." (PMID 38694821, 2024). "Compared to controls, AAA-1-immunized mice showed higher plasma CK-18 (5.3 vs. 2.1 pg/mL, p = 0.031), IL-6 (13 vs. 6.9 pg/mL, p = 0.035), IL-10 (27.3 vs. 9.8 pg/mL, p = 0.007), TNF-α (32.1 vs. 24.2 pg/mL, p = 0.032), and liver steatosis (93.4% vs. 73.8%, p = 0.007)." (PMID 39595946, 2024). "C20 could reverse the impact of the HFD on both cytokines; however, Z1T1, which effectively reversed diet-induced weight gain and hepatic steatosis, lowered only the level of TNF-α in the liver." (PMID 37317266, 2023). "In this regard, we may hypothesize that TNF-α initially induces inflammation by activating NF-κΒ, as a counteracting mechanism against hepatic steatosis; this mechanism initially seems to protect against hepatocarcinogenesis (through NF-κΒ signaling)." (PMID 37958479, 2023). "Moreover, treatment of NAFLD mice with anti-TNF antibody or selective anti-TNFR1 antibody attenuated hepatic steatosis." (PMID 37407724, 2023). "While ATF3 is the inducer of RIPK3, TNFα is a vital activator of RIPK3 in hepatic steatosis." (PMID 36690638, 2023). "Remarkably, the present work shows that MaR1 is able to reverse the decrease in ADIPOQ expression induced by HFD in DIO mice and by TNF-α in both models of cultured human adipocytes, which potentially contribute to a parallel improvement on insulin sensitivity or alleviation of hepatic steatosis." (PMID 37371501, 2023). "For example, compared to WT, female Fpr2−/− mice in a dietary model of non-alcohol-associated fatty liver disease had enhanced hepatocellular death and inflammation, as shown by elevated hepatic TNFα levels." (PMID 37237453, 2023). "Moreover, dapagliflozin treatment reduced the expression of hepatic inflammatory cytokine (TNF-α, IL-1β, IL-18) content and improved hepatic steatosis in HCHF fed male Wistar rats." (PMID 35328527, 2022). "Moreover, they found a significant decrease in tumor necrosis factor-α, nuclear factor-kB, and hepatic steatosis." (PMID 35955942, 2022). "Overall, the results of this study demonstrated that CSP could attenuate hepatic steatosis and decrease liver inflammation via the TNFα/TNFR1 signaling pathway in mice with HFHFD plus CIS." (PMID 36172180, 2022). "In addition to oxidative stress, inflammation mainly contributes to liver disease and pro-inflammatory factors such as IL6 and TNF-α significantly increase fatty liver disease." (PMID 36159326, 2022). "Also, EtOH-treated mice had marked increases in hepatic steatosis, liver injury, and expression of pro-inflammatory mediators, including TNF-α, and TLR4-positive macrophages, Kupffer cells, and hepatocytes in the intestines and liver, respectively." (PMID 33815111, 2021).
Hepatic steatosis (continued). "In addition, the effect of butyrate and α-lipoic acid (ALA), which are substances that are known to inhibit fatty liver, and tumor necrosis factor-α (TNF-α), which is a substance known to promote the fatty liver disease, was examined." (PMID 34703969, 2021). "Our results confirm that male APOB-100 transgenic animals show more severe metabolic disturbances after 7 months of an HFD compared to females, with regard to, for example, fasting glucose, serum triglyceride (TG), tumor necrosis factor α (TNFα) levels, and hepatic steatosis." (PMID 33919597, 2021). "In addition, TNF-α can also induce liver steatosis by inhibiting the activity of AMP-activated protein kinase (AMPK), activating SREBP-1c, and upregulating the expression of acetyl-Coenzyme A carboxylase (ACC) as well as FA synthase (FAS)." (PMID 34966296, 2021). "Enhancement of TNF–α signalling may be critical in the pathogenesis of hepatic steatosis and fibrosis, blockade of TNFR1/TNFR2 signalling is a promising therapeutic target for NAFLD." (PMID 34836315, 2021). "In addition to TGF-β, other cytokines, such as IL-1, IL-6, and TNF-α, contribute significantly to the pathophysiology of hepatic steatosis through stimulation of hepatic inflammation, and can in turn promote CRLM." (PMID 33767997, 2021). "Moreover, it alleviates hepatic steatosis inflammation via the inhibition of the hepatic TNF-α production." (PMID 32256346, 2020). "Furthermore, hepatic steatosis and levels of TNF-α, IL-6, IL-1β inflammatory genes increased in OVX rats, but were reduced after BCE intake." (PMID 32466275, 2020). "Indeed, one of the factors involved in the genesis and maintenance of hepatic steatosis is the influx of bacterial products, leading to activation of the hepatic systems that initiate damage with TNF-α release or reduction of cell function by Kupffer cells." (PMID 32098159, 2020). "The comparison between HFD and LPS treatment suggests that TNF, regardless of the cause of its release, is the major mediator of hepatic steatosis." (PMID 33050035, 2020). "Furthermore, TNF-α is considered to be the major cytokine in the progression of simple fatty liver to NASH." (PMID 30757944, 2019). "Equally important studies from Anna Mae Diehl's laboratory showed that the use of a certain probiotic decreased hepatic steatosis to a similar extent than treatment with an anti-TNF antibody suggesting that both microbes and inflammatory pathways contribute to evolution of hepatic steatosis." (PMID 31555219, 2019). "In addition to its tissue direct effects on IR, TNF regulates pro-inflammatory markers, such as IL-6 and lipocalin-2 (LCN2) that are implicated in the pathogenesis of hepatic steatosis and T2D onset and progression." (PMID 31892368, 2019). "Moreover, according to a recent study, RBP4 induces hepatic steatosis because it activates primary inflammatory effects in adipose tissue and stimulates proinflammatory cytokines, such as TNF-α, while the suppression of RBP4 prevented NAFLD in mice models." (PMID 30096951, 2018). "Thus, besides TNFα-reduction in the liver imatinib leads to early changes in lipid metabolism, which is later followed by markedly decreased hepatic steatosis." (PMID 30333571, 2018). "Therefore, questions remain regarding the necessity of TNFα signaling in the etiology of bovine fatty liver disease." (PMID 29344353, 2018). "Also, the importance of TNF-α in human and animal fatty liver diseases, both due to genetic manipulation and over-nutrition, has been demonstrated." (PMID 30024933, 2018). "However, the dietary treatments significantly decreased hepatic steatosis and inflammation mediated by tumor necrosis factor-α (Tnf-α) with respect to the HFS group." (PMID 28680065, 2017).
Hepatic steatosis (continued). "A previous study indicated that fish oil could reduce ethanol-induced fatty liver and hepatic production of the inflammatory cytokines, IL-6 and TNF-α, consistent with the reduction of IL-6 having a protective effect against ethanol-induced hepatic steatosis." (PMID 27143963, 2016). "Similarly, other studies have shown that alcohol-mediated fatty liver and injury are prevented by PPARγ agonist presumably by activating c-Met and blocking alcohol-mediated induction of TNFα." (PMID 28074114, 2016). "The main causes for alcoholic fatty liver are known to be accumulation of acetaldehyde, tumor necrosis factor α, endoplasmic reticulum stress, 2-arachidonoylgycerol, and adenosine, which increase SREBP1c activity and induce fatty acid synthesis, leading to alcoholic fatty liver." (PMID 27404390, 2016). "Considering the importance of TNF-α in the development of alcoholic fatty liver, suppression of TNF-α secretion by licorice may contribute to its overall preventive effect in alcoholic liver injury." (PMID 26801973, 2016). "Moreover, osthole inhibits TNF-α production and showed anti-oxidative ability in alcohol-induced fatty liver in mice." (PMID 26231226, 2015). "Thus, the soybean diet prevented hepatic steatosis at least in part through reduced lipogenesis but resulted in TNFα-mediated inflammation." (PMID 25892856, 2015). "Adiponectin and TNF-α play important roles in the development of liver steatosis." (PMID 26101535, 2015). "In addition, inhibition of hepatic tissue necrotic factor a (TNFα) improves steatosis in ob/ob mice, and decreasing the expression of interleukin-10 (IL-10) derived from Kupffer cells can improve hepatic steatosis." (PMID 25672270, 2015). "More recent reports have indicated that the symptoms of fatty liver disease can be improved by Magnolia officinalis extract via suppression of tumor necrosis factor α (TNF-α), superoxide anion, and sterol regulatory element-binding transcription factor 1c (SREBF1c)." (PMID 25849950, 2015). "Authors think that the decreased liver damage in a model of liver steatosis could be related to its anti-TNF-α effect." (PMID 25937854, 2014). "The attack of the organ also involves oxidative stress, causing peroxidation of membrane lipids in the hepatocytes and cytokine production, especially of tumor necrosis factor alpha (TNF-α), which are partly responsible for the progression of hepatic steatosis to steatohepatitis and cirrhosis." (PMID 23496920, 2013). "Extensive evidence supports a central role of TNF-α and other pro inflammatory cytokines in development of fatty liver, but several reasons might explain the discrepancies." (PMID 24358045, 2013). "TNFα has been shown to induce fat accumulation in the liver resulting in hepatic steatosis." (PMID 20140224, 2010). "TNFα induces hepatic steatosis in mice with increased hepatic lipid synthesis." (PMID 20140224, 2010). "Our purpose now was to investigate first whether resveratrol decreased hepatic steatosis in an animal model of steatosis, and second, whether this therapeutic approach resulted in a decrease in tumor necrosis factor α (TNF-α) production and oxidative stress." (PMID 18782455, 2008). "We therefore think that the decreased liver damage in a model of liver steatosis could be related to its anti-TNF-α effect." (PMID 18782455, 2008). "Our purpose was to investigate whether resveratrol decreased hepatic steatosis in an animal model of steatosis, and whether this therapeutic approach resulted in a decrease in tumor necrosis factor α (TNF-α) production, lipid peroxidation and oxidative stress." (PMID 18782455, 2008). "Consistently, excessive lipid accumulation could further promote TLR4/NF‐κB signaling to trigger the leakage of proinflammatory cytokines (TNF‐α, IL‐6, IL‐1β, and IL‐18), thus exacerbating the vicious cycle of inflammatory responses in the liver to aggravate fatty liver progression." (PMID 40501499, 2025).
Hepatic steatosis (continued). "Hepatic steatosis perturbs mitochondrial homeostasis and activates nuclear factor kappa B (NF-κB), thereby amplifying inflammatory cascades and inducing the release of cytokines such as tumor necrosis factor-α (TNF-α), interleukin-6 (IL-6), and interleukin-1β (IL-1β)." (PMID 41150795, 2025). "In addition, DCA and LCA were reported to potentially increase gut permeability and increase the exposure of the liver to gut-derived toxins, which can increase proinflammatory cytokines (TNF-α and IL-6), thereby promoting inflammation and hepatic steatosis in animal models of NAFLD." (PMID 37202792, 2023). "In addition, TNF-α stimulates hepatocyte death and the progression of fatty liver disease." (PMID 36765351, 2023). "TNF-α increases hepatic cholesterol synthesis and suppresses its elimination, which results in a dramatic increase in LDL cholesterol and a decrease in HDL cholesterol, while a TNF-α blocking antibody alleviates hepatic steatosis in ob/ob mice that have a leptin deficiency." (PMID 34956171, 2021). "Finally, Kamut could significantly improve the liver steatosis grade by reducing circulating proinflammatory TNF-α, IL-8, interferon-gamma (IFNγ), and the interleukin-1 receptor antagonist (IL-1RA)." (PMID 34426744, 2021). "Although ASAH2 may improve insulin sensitivity and hepatic steatosis and inhibits TNF-α-induced vascular inflammation, only a few studies have targeted the manipulation of ASAH2 expression as a therapeutic approach, as ASAH2 distribution and its functions remain unclear in many respects." (PMID 31817238, 2019). "We believe that improvement in mitochondrial function and browning (evidenced by UCP1 and PGC1A upregulation) of white fat may have helped to reduce the systemic inflammation (as seen with TNFα plasma values reduction) with subsequent ameliorating of fatty liver disease." (PMID 31477174, 2019). "Therefore, the inhibition of TGF-β1, TGF-β2 and TNF-α expression by PSEs may partly explain its role in preventing the progression of liver steatosis to fibrosis and NASH." (PMID 28169366, 2017). "In addition, we observed increased fasting glucose levels and circulating triglycerides, along with high TNF-α production in adipose tissue and increased total fat, cholesterol and triglyceride contents in the liver, contributing to higher intensity of hepatic steatosis." (PMID 28265495, 2017). "In addition, elevated levels of TNF-α, IL-6 and MCP-1 were associated with the development of NAFLD, and pharmacological and genetic inhibition of these pro-inflammatory mediators ameliorated hepatic steatosis in obese animals." (PMID 27213439, 2016). "Given that inactivation of Kupffer with gadolinium chloride prevents ethanol-induced fatty liver disease in rats, any reduction in the efficacy of adiponectin to promote IL-10 and reduce TNFα could promote the fatty liver phenotype afflicting dolphins with iron overload." (PMID 24065958, 2013). "Compared with HFHC, both CAB and HECAB reduced serum insulin and HOMA-IR, attenuated hepatic steatosis, increased SOD1 and CAT, and reduced NF-κB, IL-6, TNF-α, and IL-1β, whereas GPx1 remained unchanged." (PMID 42193214, 2026). "Our data reveal that TNF’s disruptive hepatic mitochondrial FFA β-oxidation is aggravated in Slc25a13-/- mice, leading to accelerated circulatory FFA accumulation and hepatic steatosis." (PMID 41132685, 2025). "Across studies, key parameters measured include liver steatosis (via histology), serum liver enzymes (ALT/AST), pro-inflammatory cytokines (e.g., TNF-α, IL-6), insulin resistance markers, and gut microbial composition." (PMID 41001122, 2025). "In this regard, transgenic NAFLD mice lacking TNF-α receptors (tnfr−/−) were protected from severe hepatic steatosis, whereas treatment of NAFLD mice with anti-TNF antibody or selective anti-TNFR1 antibody attenuated hepatic steatosis." (PMID 40794228, 2025).
Hepatic steatosis (continued). "In vivo, 3d (30 mg/kg) lowered serum TG (39% decrease), TC (32% reduction), LDL-C (45% decline), and TNF-α (57% reduction) in HFD-fed mice (p < 0.05 vs. model), normalized AST/ALT levels, and ameliorated hepatic steatosis, ballooning, and fibrosis." (PMID 40422873, 2025). "There was a significant association between astaxanthin intake and reduced liver fat accumulation, hepatic steatosis, LDL‐C, TG, AST, ALT, IL‐1, TNF‐α, IL‐6, and macrophage inflammatory protein −2 levels." (PMID 40071130, 2025). "For instance, aguamiel concentrate (AC) from Agave salmiana (A. salmiana) was shown to reduce hepatic steatosis by increasing plasma ALT, decreasing hepatic lipid accumulation, reducing hepatic TNF-α, and decreasing MDA." (PMID 39451562, 2024). "Blocking the IKK ɛ and TBK1 pathways can significantly reduce the inflammatory factors produced by pro-inflammatory cells such as TNF- α and MCP-1, thereby improving insulin sensitivity and reducing liver steatosis." (PMID 38436022, 2024). "Primary outcomes included improvement in hepatic steatosis and ALT activity, while secondary outcomes included changes in AST activity, blood lipids, glucose, BMI, blood pressure, and TNF‐α." (PMID 39723101, 2024). "The contribution of hepatic inflammation to chronic diseases such as MASLD (previously known as NAFLD) is supported by the experimental evidence that TNF-α-/- mice and mice treated with a TNF-α receptor antagonist are resistant to hepatic steatosis." (PMID 38613016, 2024). "This occurs by means of the portal inflow of TLR-4 and TLR-9 agonists in mice, leading to heightened hepatic tumor necrosis factor alpha (TNF-α) expression and inflammation, a phenomenon particularly pronounced in mouse models of hepatic steatosis." (PMID 38613058, 2024). "Knockout of miR-34a in HFD-fed obese mice attenuated VAT fibrosis, local (WAT CLS formation/M1 polarization) and systemic (serum cytokines: TNF-α, IL-6, IL-1β, and MCP-1) metaflammation, insulin resistance, and hepatic steatosis." (PMID 39063184, 2024). "Significantly reduced the fatty liver index, serum GGT and AST values; diminished chronic systemic inflammatory state; and lowered IL-6 and TNF-α concentrations in NAFLD patients." (PMID 38398870, 2024). "Compared to WT mice, TRIF knockout mice exhibited decreased serum levels of TNF-α and ALT, as well as ameliorative liver steatosis." (PMID 38694821, 2024). "Whereas, with increased hepatic steatosis, the transcription factor ATF3 also increases hepatocyte death by inducing RIPK3 expression and changing the TNFα-dependent cell death pattern from apoptosis to necroptosis." (PMID 39244571, 2024). "A “Symbiter” containing 14 live probiotic strains of Acetobacter, Propionibacterium, Bifidobacterium, and Lactobacillus + Lactococcus improved tumor necrosis factor (TNF)-α, IL6, aminotransferase activity, and hepatic steatosis in NAFLD patients." (PMID 38398870, 2024). "Acute ethanol-induced hepatic steatosis was alleviated, and the hepatic expression of SREBP-1c and plasma levels of TNF-α, IL-6, and MCP-1 were reduced in fat-1 transgenic mice." (PMID 38791514, 2024). "In the pathogenesis of NAFLD and NASH, tumor necrosis factor-alpha (TNF-α) assumes a pivotal role by intensifying inflammation and contributing to hepatic steatosis, oxidative stress, and hepatocyte apoptosis." (PMID 39055878, 2024). "The activation of this inflammatory pathway results in the release of substantial amounts of tumor necrosis factor-alpha (TNF-α), which contributes to lipid peroxidation and fibrosis in hepatocytes, thereby promoting the progression of fatty liver disease." (PMID 39335920, 2024). "↓BW, BMI, TCHO, TG, LDL, LPS, TNF-α, and total bile acid; ↑HDL, organ index, liver steatosis, small intestine structure." (PMID 37396125, 2023). "↓BWG, FBG, insulin, HOMA-IR value, serum LPS, hepatic steatosis, adipocyte hypertrophy; ↑HDL-C level; ↓Ileum IL-6 and TNF-α levels; ↑↓Ileum IL-10 levels." (PMID 37396125, 2023).